CRP (C-reactive protein)
Diseases named in the same sentence as CRP in open-access papers (continued):
Sharing a sentence is not in itself a finding about the gene and the disease.
Pleural effusion (continued). "We planned a comparative analysis to assess the predictive accuracy and diagnostic significance of PCT and PTX-3 compared to established biochemical markers (CRP and ADA) in the early differential diagnosis of pleural effusions." (PMID 34179342, 2021). "We evaluated two established (ADA, CRP) and two more recent biomarkers (PTX-3 and PCT) in serum and pleural fluid separately to find their accuracy and efficiency to discriminate pleural effusion." (PMID 34179342, 2021). "The main strength of this study is the possibility of diagnosis and discrimination of pleural effusions using cost-effective and widely available biomarkers (p-ADA, p-CRP)." (PMID 34575641, 2021). "Elevated levels of CRP and ESR showed a high prevalence in patients with PCIS, with pleural effusion occurring in every second patient." (PMID 32170340, 2020). "This was continued for one week and a regression of pleural effusion was demonstrated on chest radiography with a normalization of inflammatory parameters (ESR and CRP) and peripheral blood counts." (PMID 30967975, 2019). "Univariate analysis showed biomarkers of systemic inflammation, such as serum CRP, and pleural inflammation, such as pleural fluid LDH to be raised in pleural effusion of infectious aetiology such as TB and parapneumonic effusion." (PMID 26678281, 2016). "Univariate analysis identified duration of fever, peak body temperature, pleural effusion, rash, WBC, N%, L%, PLT, LDH, CRP, CD3+ cells, CD3 + CD4+ cells, CD3 − CD19+ cells and CD19 + CD23+ cells as significant corticosteroid-resistant RMPP risk factors." (PMID 28008989, 2016). "The RMPP group exhibited more severe symptoms, longer fever and hospital stays, higher inflammatory markers (CRP, LDH, D-dimer, ESR, PCT; P < 0.001), and more frequent pulmonary consolidation, pleural effusion, plastic bronchitis, and extrapulmonary involvement." (PMID 41610122, 2026). "Patients with pleural effusion had significantly higher CRP levels (9.80, IQR 4.44–14.3) compared to those without pleural effusion (2.71, IQR 1.46–8.25), with a p-value of 0.001, indicating a higher inflammatory response in patients with pleural effusion." (PMID 40428888, 2025). "constructed a prediction model with relatively better predictive performance (AUC=0.867) based on age, albumin to globulin ratio (AGR), NLR, CRP, ESR, mean platelet volume (MPV), comorbid infections, pleural effusion, primary disease, duration of fever, and wheezing." (PMID 40171163, 2025). "Several biomarkers have recently been applied to the diagnosis and differentiation of TPE in China and abroad, including adenosine deaminase (ADA), lactate dehydrogenase (LDH), C-reactive protein (CRP), and several inflammatory cytokines in serum and pleural effusion." (PMID 38750432, 2024). "After applying LASSO analysis, 13 of the 29 candidate clinical parameters were further screened; 25(OH)D, length of symptoms, WBC count, D dimer, CRP, ferritin, albumin, mechanical ventilation, IL-8, ALT, pleural effusion, polylobular infection, and MP DNA copies." (PMID 36778550, 2023). "The study also noted that the white blood cell count, serum C-reactive protein level, and body temperature of patients with pleural effusion were higher than those without pleural effusion, suggesting a possible inflammatory reaction." (PMID 36698955, 2022). "These indicators include the clinical parameters such as ECOG PS, non-adenocarcinoma histology, EGFR mutation and LENT score, the serum indicators such as NLR, hemoglobin, total protein, albumin, LDH, CRP and VEGF, and the pleural effusion indicators such as PH, glucose, LDH, VEGF and surviving." (PMID 35209915, 2022). "Fourthly, due to the lack of relevant indicators of SUVmax, CRP and pleural effusion, we did not include the SUVmax, LENT score, PROMISE score and other indicators as independent variables in COX univariate analysis." (PMID 36557076, 2022).
Pleural effusion (continued). "Adenosine deaminase (ADA) activity, lymphocyte count, lactate dehydrogenase (LDH), and C-reactive protein (CRP) of pleural effusion in pleural TB group were higher than in the no pleural TB group (all p-values < 0.05)." (PMID 35250926, 2022). "C-reactive protein (OR = 1.089, P = 0.433) or age (OR = 0.998, P = 0.921) did not predict the origin of pleural effusion." (PMID 35777003, 2022). "The aim of this study was to determine whether the pleural levels of two biological markers, ADA- CRP, and their combined function, could help us discriminate malignant (MPE), parapneumonic (PPE) and tuberculous (TPE) pleural effusions." (PMID 34575641, 2021). "As inflammatory indexes such as WBC, CRP, LDH, and DD increased and pleural effusion was formed, and there may be excessive immune inflammatory reaction mediated by cytokines, most children were given different doses of glucocorticoids at the same time." (PMID 34376156, 2021). "CRP ≥ 44.45 mg/L, LDH ≥ 590 IU/L, FER ≥ 411 ng/L, neutrophil≥73.75%, lung consolidation, and pleural effusion may be predictors that guide the treatment of RMPP with pulse dose of GC." (PMID 33509121, 2021). "In addition to these modalities, there are at least two biomarkers showing promising results in the early diagnosis of pleural effusions: adenosine deaminase (ADA) and acute-phase proteins like C-reactive protein (CRP)." (PMID 34179342, 2021). "The mean C-reactive protein, lactate dehydrogenase, and aspartate aminotransferase levels were significantly higher in the pleural effusion group than in the non-pleural effusion group at admission." (PMID 34578108, 2021). "This study found that CRP 44.45 mg/L, LDH 590 IU/L, FER 411 ng/L, leukocyte classification neutrophil 73.75%, lung consolidation and pleural effusion may be important clinical features of use pulsed dose hormones to treat RMPP." (PMID 33509121, 2021). "The primary aim of the study was to assess the predictive accuracy of procalcitonin (PCT) and pentraxin-3 (PTX-3) in comparison to other biochemical markers such as C-reactive protein (CRP), and adenosine deaminase (ADA) in the differential diagnosis of pleural effusions." (PMID 34179342, 2021). "In summary, this study showed that pleural fluid presepsin, CRP, and PCT levels may be of value as additional tools in the assessment of pleural effusions to support the differential diagnosis." (PMID 30470216, 2018). "Procalcitonin levels were significantly higher in the pleural infection group than those with non-infective (malignant) pleural effusions, even when case-matched for their CRP, age and gender." (PMID 23251353, 2012). "Additionally, the SMPP and RMPP groups exhibited higher levels of C-reactive protein (CRP), white blood cells (WBC), platelets, neutrophil-to-lymphocyte ratio (NLR), lactate dehydrogenase (LDH), and D-dimer, and a higher incidence of pleural effusion (P < 0.05)." (PMID 41313182, 2026). "Therefore, utilizing parameters such as ADA, LDH, CRP, and ESR together could enhance the accuracy of distinguishing between TPE and pleural effusions of other origins." (PMID 38750432, 2024). "Finally, we attempted to categorize pleural effusions based on both ADA and CRP levels." (PMID 34575641, 2021). "CRP ≥ 44.45 mg/L, LDH ≥ 590 IU/L, FER ≥ 411 ng/L, neutrophil≥73.75%, lung consolidation, and pleural effusion may be meaningful predictors that guide the treatment of RMPP with pulse dose of GC, which can reduce the incidence of severe RMPP and the occurrence of severe sequelae." (PMID 33509121, 2021). "Additionally, high CRP levels (cut-off: 10 mg/dL) have been used as differentiator between complicated and non-complicated parapneumonic pleural effusions, with comparable AUC scores to those of widely accepted pleural pH and glucose." (PMID 34575641, 2021).
Pleural effusion (continued). "Never smoking, high CRP, liver metastasis, pleural effusion, and steroid use at the commencement of nivolumab treatment were predictive of worse PFS in patients with NSCLC who received nivolumab treatment with good PS, and a high ALI was predictive of better PFS in patients with poor PS." (PMID 31880861, 2020). "In patients with NSCLC treated with nivolumab, the factors found to be predictive of shorter PFS in patients with good PS were never smoking, high CRP, liver metastasis, pleural effusion, and steroid administration, whereas high ALI was predictive of longer PFS in patients with poor PS." (PMID 31880861, 2020). "Never smoking, CRP ≥ 1 mg/dL, liver metastasis, pleural effusion, and steroid use were predictive of shorter PFS in patients with NSCLC treated with nivolumab with good PS, whereas ALI ≥ 18 was predictive of longer PFS in patients with NSCLC treated with nivolumab with poor PS." (PMID 31880861, 2020). "The results indicated that WBC AST, ALT, CRP, IL-6, ESR, the duration of fever, and pleural effusion showed no significant publication bias, while LDH, neutrophil percentage, and lung consolidation showed evidence of publication bias." (PMID 40656195, 2025). "For example, a 54-month-old child with MPP has an 87.1% probability of SMPP, whose characteristics were fever days ≥ 7, AGR of 2, NLR of 3, CRP 20 mg/L, ESR 38 mm/h, MPV of 10 fL, coinfection, primary disease, no pleural effusion, and no wheeze." (PMID 38589453, 2024). "The univariate analysis showed significant differences between the embolism group and non-embolism group in Tmax, CRP, D-dimer (closest to CTA/MRA), N%, pulmonary consolidation (⩾ 2/3 lobe), pleural effusion and atelectasis(P < 0.05)." (PMID 35987653, 2022). "Serum C-reactive protein (CRP) and lactate dehydrogenase (LDH) are more elevated in patients with pleural effusion than in those without pleural effusion." (PMID 35268372, 2022). "Similarly, in the PE group, the pre-hospital fever duration, CRP, LDH, NLR, and D-dimer levels, along with the incidence of pleural effusion, were all significantly higher than in the non-PE group." (PMID 41313182, 2026). "Cough and dyspnea were not included because these symptoms could be presented after pleural effusion occurred, and protein, ALP, ESR and CRP were also not included to eliminate the influence of multicollinearity." (PMID 27287396, 2016). "The right pleural effusion on the chest CT 2 months postoperatively did not worsen; and no fever or elevated inflammatory response was observed (WBC, 4710/μL; Neut, 84.5%; CRP, 0.21 mg/dL), the infection was considered controlled, and the oral vancomycin was discontinued." (PMID 39517010, 2024). "The levels of C-reactive protein (CRP), lactate dehydrogenase (LDH), and aspartate aminotransferase (AST) at the time of admission were significantly higher and the level of lymphocytes (%) was significantly lower in the pleural effusion group than in the non-pleural effusion group." (PMID 34578108, 2021).
systemic lupus erythematosus (183 papers, 2007 to 2026). An autoimmune multi-organ disease typically associated with vasculopathy and autoantibody production. "And high CRP levels were associated with high cardiometabolic risk and clinical disease activity in systemic lupus erythematosus (SLE) patients." (PMID 38302903, 2024). "By contrast, osteoarthritis and lupus, respectively, have well-established positive and negative clinical links with CRP, and, interestingly, both were associated with circulating CRP concentrations in the corresponding directions in the current analysis." (PMID 39013416, 2024). "Recently, a study represented higher titer of CRP as a potential risk factor of sacroiliac involvements in lupus patients." (PMID 38952465, 2024). "Systemic lupus erythematosus (SLE) patients have a higher frequency of cardiovascular risk factors such as high C-reactive protein (CRP) levels than the general population." (PMID 35407457, 2022). "CRP levels have also shown to reflect tissue damage in many diseases; a large study on 610 patients with systemic lupus erythematosus found an association between increased CRP levels and different types of organ damage, including myocarditis." (PMID 36498643, 2022). "Vitamin D status has been suggested to be inversely associated with CRP in asymptomatic, elderly, obese adults and children with lupus in previous cross-sectional studies." (PMID 26569292, 2015). "The top marker (rs1341665, p = 2.82×10−16, 0.692 mg/L average increase per G allele) is in strong LD with several variants, including rs1205, a 3-prime flanking region SNP previously implicated in CRP expression and systemic lupus erythematosus susceptibility." (PMID 22291609, 2012). "Notably, CRP levels were influenced by both BMI and Alistipes, particularly in lupus individuals with higher BMI, and elevated IL-6 was associated with higher CRP in this subgroup." (PMID 41289287, 2025). "Previous report indicated that CRP-lowering polymorphism rs1205 could associate the low CRP levels in lupus patients." (PMID 36319843, 2022). "Moreover, an association between increased BAFF and CRP levels in the serum was reported in patients with systemic lupus erythematosus (SLE)." (PMID 30053824, 2018). "One possible explanation for the observed association between Alistipes abundance and elevated CRP in lupus patients with higher BMI is that certain species of Alistipes may produce pro-inflammatory metabolites, such as lipopolysaccharides or short-chain fatty acids that modulate immune responses." (PMID 41289287, 2025). "The study included middle aged women with Systemic Lupus Erythematosus (SLE) and demonstrated positive association between C3 and CRP on the one hand with aortic stiffness on the other." (PMID 28759613, 2017). "CRP levels are influenced by BMI and Alistipes shahii abundance, especially in lupus individuals with higher BMI." (PMID 41289287, 2025). "CRP levels are affected by BMI and Alistipes shahii abundance in lupus patients, but as Alistipes shahii level increases, CRP concentration substantially increases more in subjects with high BMI." (PMID 41289287, 2025). "The observed variations in CRP response may be associated with polymorphisms and down-regulation in certain diseases, like systemic lupus erythematosus (SLE)." (PMID 41460264, 2025). "A growing number of clinical trials have shown that CRP is related to many diseases, including cardiovascular disease, atherosclerotic vascular disease, systemic lupus erythematosus, cancer, and other diseases." (PMID 40317383, 2025). "Elevated D-dimer (>3 μg/mL), C-reactive protein, ferritin, white blood cell count, and IL-6; Lupus Anticoagulant positivity; fibrinogen > 8 g/L." (PMID 40564053, 2025). "Autoantibodies targeting CRP are common in patients with systemic lupus erythematosus (SLE) and the levels correlate with disease activity." (PMID 40443658, 2025).
systemic lupus erythematosus (continued). "Another study demonstrated that a higher ratio of monomeric to pentameric CRP enabled researchers to differentiate between active and quiescent disease states in patients with systemic lupus erythematosus." (PMID 39867895, 2024). "For example, in systemic lupus erythematosus, biomarkers such as IL-18 and TNFα are preferred over CRP for disease monitoring." (PMID 37476185, 2023). "Higher plasma CRP levels were found to predict flares in systemic lupus erythematosus and to portend poor prognosis in melanoma." (PMID 37564640, 2023). "The binding of CRP with circulating IgG immune complex has been found to increase the exposure of fucosyl residues in systemic lupus erythematosus patients." (PMID 36233595, 2022). "CRP level data was taken from Hasan Sadikin lupus registry data, and MDA levels were analyzed from a bioarchive patient's serum." (PMID 32695177, 2020). "We collected the patients' data who had CRP level from Hasan Sadikin lupus registry and analysed MDA levels from the serum sample." (PMID 32695177, 2020). "Based on the results of the analysis, the coefficient of η = 0.127 was obtained in the correlation of CRP with lupus nephritis, η = 0.083 with lupus cutaneous, and η = 0.066 with lupus musculoskeletal." (PMID 32695177, 2020). "Patients with active SLE also displayed higher GlycA levels than non-lupus KD controls (n = 21, p = 0.04), despite comparable CRP levels, and despite a more altered renal function in KD controls (p < 10−3)." (PMID 32244481, 2020). "Together with serum uric acid, increased in the metabolic syndrome, secondary inflammation in obese lupus patients sustains a vicious cycle of oxidative stress through increased CRP gene expression and elevated protein oxidation and lipid hydroperoxidation." (PMID 31137916, 2019). "Another study found that 28% of lupus patients are overweight and 39% are obese, and carriers of higher concentrations of inflammatory markers including C-reactive protein (CRP)." (PMID 31137916, 2019). "Connective tissue diseases, including systemic lupus erythematosus, Sjogren’s syndrome, and myositis, were attributed by the treating rheumatologist to the elevated CRP in 10% of cases." (PMID 29855349, 2018). "Autoantibodies against monomeric C-reactive protein (anti-CRP-Ab) observed in patients with systemic lupus erythematosus (SLE) and lupus nephritis (LN) were suggested to be associated with active LN and a poor response to therapy during short-term follow-up." (PMID 26704903, 2015). "While a hallmark of inflammation is the elevation in levels of C-reactive protein (CRP), many lupus patients demonstrate normal or even reduced levels of CRP." (PMID 26579125, 2015). "Taken together, these findings have led to the conclusion that the CRP response in lupus is less than what is expected and CRP serum concentrations were not correlated with disease activity or with any types of clinical manifestations." (PMID 26613049, 2015). "From the other hand, systemic lupus erythematosus is one exception to the generalization that C-reactive protein concentrations correlate with the severity of inflammation." (PMID 24346772, 2014). "Serum levels of C-reactive protein (CRP) seldom reflect disease activity in systemic lupus erythematosus (SLE)." (PMID 20003354, 2009). "The presence of autoantibodies against CRP in lupus was originally described by Frank A Robey and coworkers in 1985." (PMID 20003354, 2009). "The dramatic presentation in our case with tamponade could be, in part, related to a predominant serositis, reflected by the very raised CRP, which would normally be expected to be only moderately raised in lupus flares." (PMID 40750142, 2025). "The results in this study are limited to linear epitopes, and future research should investigate the role of specific anti-CRP autoantibodies with different antigen reactivities (including discontinuous epitopes) in lupus pathogenesis and in relation to different organ manifestations." (PMID 40443658, 2025).